AR (androgen receptor)
Diseases named in the same sentence as AR in open-access papers (continued):
Sharing a sentence is not in itself a finding about the gene and the disease.
breast carcinoma (continued). "In the present study, there was a negative correlation between AR overexpression and pathologic tumor size, in agreement with results reported in human breast cancer." (PMID 31888566, 2019). "We did detect HULLK in the ER + AR+ luminal A subtype MCF7 breast cancer (BCa) cell line but not in the triple negative Claudin-low BT549 or MDA-MB-231 BCa cell lines." (PMID 31253147, 2019). "If breast cancer patients are removed from the set of all other patients analysed here, ER and PR are still significant predictors of importance, but AR is no longer a significant predictor of outcome." (PMID 29507702, 2018). "ARA 70 has also been shown to interact with ERα and may play a role in modulating AR and ERα activity in MCF7 breast cancer cells." (PMID 30416486, 2018). "Our data suggest that AR should be added to the current set of ER, PR, and HER2 markers for breast cancer classification, and AA “QNBC” breast cancer patients could be candidates for immune targeted therapies." (PMID 29912871, 2018). "In molecular apocrine breast cancer, ERK and AR have a feedback loop that results in co-regulation." (PMID 30416486, 2018). "In this study, we examined expression of AR and VDR, phosphorylation of AKT serine (Ser) 473 (AKT phospho-Ser473) and ERα Ser167 (ERα phospho-Ser167) by immunohistochemistry in ER-positive, HER2-negative early breast cancer." (PMID 29707142, 2018). "There was also little evidence for an interaction between AR levels and those of the estrogen receptor or the proliferation marker Ki67 on the incidence of breast cancer." (PMID 30276234, 2018). "We likewise found little evidence for an interaction between AR and ER expression in normal breast TDLUs with respect to the incidence of breast cancer." (PMID 30276234, 2018). "Androgen receptor (AR) is expressed in 60%~ 70% oestrogen receptor (ER)-negative breast cancer (BC) cases and promotes the growth of this cancer subtype." (PMID 30217192, 2018). "Epithelial AR expression was assessed by immunohistochemistry in normal tissue from the BBD biopsy and the percent of positive nuclei was estimated in ordinal categories of 10% for 78 breast cancer cases and 276 controls." (PMID 30276234, 2018). "A major concern with clinical trials assessing the efficacy of anti-AR therapies in breast cancer is that, currently, we do not have a standardized cut-point for AR positivity." (PMID 30416486, 2018). "Taken together, our data suggests that AR is expressed in many breast carcinomas, however unlike SOX10, it cannot be used as an independent biomarker." (PMID 30279965, 2018). "Where one study indicates a lack of correlation between AR expression and male breast cancer, another indicates decreased AR expression is correlated with earlier development of cancer." (PMID 28245550, 2017). "In addition, this model implicates a potential role for AR signaling in the pathobiology of thromboembolic events and regulation of FVII/TF signaling in breast cancer." (PMID 28915724, 2017). "Further assessment of the prognostic role of AR in ERα-negative breast cancer with well-designed clinical studies is required." (PMID 28474005, 2017). "Unlike breast cancer, however, in SDCs, the expression of ERα and PR is almost exclusively negative, while AR is known to be frequently expressed, as noted in our results." (PMID 28938615, 2017). "In contrast, our results support a model that AR activation may be important for maximal HER2 activation without affecting the expression of HER2 and HER3 in a subset of HER2 + breast cancer." (PMID 29109513, 2017). "No such radiosensitization was seen in the AR-negative TNBC cell lines MDA-MB-231, MDA-MB-468, or the AR-negative, estrogen-receptor (ER)-positive breast cancer cell line T47D." (PMID 28840192, 2017). "Furthermore, AR acts as a transcriptional activator of PIP, a characteristic biomarker in breast cancer, which is required for cell cycle progression in both ER-positive and ER-negative breast cancer cells." (PMID 28915724, 2017).
breast carcinoma (continued). "Alternatively, ERα-negative and AR-positive breast cancers fall into a category termed the “molecular apocrine” subtype, with typically distinct histological features of eosinophilic and granular cytoplasm." (PMID 28245550, 2017). "Several larger studies and meta-analyses reviewing the prognostic implications of AR-positive breast cancer report their findings without discussion of AR in relation to co-receptor status, or male breast cancer." (PMID 28245550, 2017). "It is interesting to speculate that functional interactions between FOXP1 and the nuclear hormone receptors AR and ER17 may play a role in the 3p13-14 deletion’s prognostic significance in prostate and breast cancers and potentially others." (PMID 29057879, 2017). "Androgen receptor (AR) is involved in the pathogenesis of breast cancer, but its role is not clearly defined." (PMID 28067809, 2017). "Although, ER found to regulate the transcription of genes that promote breast cancer cell proliferation, invasion, and survival, the role of AR in these processes is not known." (PMID 29254284, 2017). "Next to ERα, also PR, AR and HER2 are treatment targets in the battle against breast cancer." (PMID 28903441, 2017). "Independent of ER expression, patients with AR-positive breast cancers were found to have statistically significant improvements in OS and DFS at both 3 year and 5 year time points, including a 13.5% absolute improvement in 5 year OS and 20.7% in DFS." (PMID 28245550, 2017). "No standardized assays or guidelines for evaluating the AR expression in breast carcinoma are available at present." (PMID 29276709, 2017). "The AR is able to induce HER2/HER3 dimerization through FOXA1 (Forkhead box protein A1) in the HER2 enriched ERα-negative breast cancer cells." (PMID 28474005, 2017). "In view of the fact that C1orf64 was markedly repressed by AR activation and SPDEF was the only AR-induced gene in the tested subset, these two genes were selected to further examine as possible direct targets of AR in breast cancer cells." (PMID 28915724, 2017). "Breast cancer survival rates at 5 and 10 years were 88% and 82% for AR-negative patients, and 95% and 88% for AR-positive patients." (PMID 28245550, 2017). "Therefore, possible therapeutic strategies such as anti-androgens should be examined considering the AR, FOXA1, and ER status in breast cancer patients." (PMID 29137314, 2017). "Both AR-negative and AR-positive SDCs showed global gene expression patterns highly similar to AR-positive (also termed molecular apocrine) breast cancers." (PMID 28208703, 2017). "Further speaking to the importance of AR across breast cancer subtypes, Barton and colleagues reported that the next-generation AR antagonist enzalutamide is effective in several non-LAR TNBC subtypes." (PMID 28085048, 2017). "AR activation has also been linked to transcriptional induction of Wnt7B and activation of Wnt/β-catenin pathway in the ERα-negative/HER2-positive breast cancer cells." (PMID 28474005, 2017). "This approach ensures that different molecular subtypes of breast cancer are represented in the study and the identified genes are highly correlated with AR expression in a large non-biased model of this disease." (PMID 28915724, 2017). "Finally, we extend our review of AR and WNT signaling to the mammary gland system and breast cancer." (PMID 28134791, 2017). "In conclusion the detailed mechanisms of AR action in breast cancer, especially in ERα-negative breast cancer, still needs further elucidation for better assessing the clinical benefit of targeting AR therapies." (PMID 28474005, 2017). "AR expression is an indicator of good prognosis in breast cancer regardless of hormone receptor (HR) status." (PMID 28060723, 2017). "Unlike comparable studies in female breast cancer, AR expression was not correlated with pathologic T stage, histologic grade, or HR expression." (PMID 28245550, 2017).
breast carcinoma (continued). "The prevalence of AR expression in ERα-positive breast cancer ranged from 60% to 80% and in ERα-negative was 10% to 50%." (PMID 28474005, 2017). "Identification of phosphorylated receptors in human tumors and discovery of phospho-PR-regulated pathways (i.e., including HER2, RUNX2, AR, AHR, and PAX2) suggest novel ways to specifically target breast cancer stem cell (CSC) outgrowth as part of durable breast cancer therapies." (PMID 28412963, 2017). "We previously identified that ERα clustered with AR and ERβ in male but not female breast cancer which clustered with ERα and PR9." (PMID 28350011, 2017). "AR mediated activation of HER2/HER3 signaling led to increased activity of MYC gene activity, which increased transcriptional activity of androgen-response genes in ER-negative and AR-positive molecular apocrine breast cancers." (PMID 28245550, 2017). "According to correlation analyses between gene expression and phosphorylated protein expression in both cell lines and tumors, significant results are found that important drug targets in breast cancer, such as ESR1, PGR, HER2, EGFR and AR show high correlated mRNA and protein levels." (PMID 27556158, 2016). "Similar to the induction by estrogens, there were discrepancies in different cellular environments in breast cancer, with a correlation of AR and ZEB1 expressions being evident in ER-negative but not in ER-positive cells." (PMID 26797644, 2016). "Considering that new agonists and antagonists for the AR are available, the emergence of nonsteroidal drugs targeting the AR as a new hormonal treatment for breast cancer is almost certainly on the horizon." (PMID 27918430, 2016). "The androgen receptor as well as other markers of apocrine breast cancer is expressed by MDA-MB-231 cells but not overexpressed by the invasive subpopulation." (PMID 27626697, 2016). "We conducted our studies using 3 cell lines that represent 3 distinct types of breast cancer: ZR75-1 cells are luminal ER/PR+Her2+AR+ cells, BT549 cells are mesenchymal-like ER/PR-Her2-AR+ cells and MDA MB 231 cells are mesenchymal stem-like ER/PR-Her2-AR- cells." (PMID 27015557, 2016). "It is worth noting that, most of these results have been obtained stimulating the cells with enzymatically metabolizable androgens, such as testosterone and DHT, while non-metabolizable AR agonists are now used for the treatment of breast cancer." (PMID 26862856, 2016). "The high expression of AR in breast cancer and recent discovery and development of new nonsteroidal drugs targeting the AR provide a strong rationale for exploring it again as a therapeutic target in this disease." (PMID 27918430, 2016). "In contrast, the roles of androgen receptor (AR), which is highly expressed in all breast cancers (60-70%) regardless of ER status, remains less clearly defined." (PMID 27285752, 2016). "The importance of androgens in the treatment of breast cancer (BC) has been reported in many studies, but the role of androgen receptor (AR) remains not completely elucidated." (PMID 26862856, 2016). "This indicated that the splicing of exon 1 and exon 1b is not mutually exclusive and that novel nine exon AR transcripts (exon 1/exon 1b/exons 2–8) are expressed in breast cancer MDA-MB-453 cells." (PMID 28035996, 2016). "Overall the next few years, when results from clinical trials with enobosarm and enzalutamide will be available, are critical to provide greater clarity on the role of the AR in ER-positive and –negative breast cancers." (PMID 27918430, 2016). "Early preclinical evidence for the anti-proliferative effects was generated in 1950s when Huggins and colleagues showed shrinkage of chemically-induced mammary tumors by ovariectomy or by the administration of DHT, long before either the ER or AR had been cloned." (PMID 27918430, 2016).
breast carcinoma (continued). "Moreover, AR-FL promotes the growth of MDA-MB-453 cells and research in this model represents a key component of the basis for targeting AR signaling in breast cancer." (PMID 26554309, 2015). "Interestingly, in ER- breast cancer, ESR1 (ERα), RELA, SP1, and AR exhibit the highest degree in the network." (PMID 25996148, 2015). "We also performed limited functional analysis of AR-V7 in the MFM-223 model, which had detectable levels of AR-V7 protein and represents a less well-studied model of ERα-negative, AR-positive breast cancer." (PMID 26554309, 2015). "Furthermore, MAZ is upregulated in prostate tumors and positively regulates androgen receptor transcription, and MAZ depletion was reported to lead to reduced proliferation and increased apoptosis of prostate or breast cancer cells." (PMID 25749382, 2015). "AR is expressed in 80–90% of all breast cancers, including up to 55% of ERα-negative breast cancers overall and up to 35% of those classified as TNBC." (PMID 26554309, 2015). "For instance, AR and ESR1 are well-established endocrine receptors in breast cancer." (PMID 26618778, 2015). "Thus we propose the model that AR on DHT stimulation promotes proliferation and decreases cell death to help in the process of breast cancer progression." (PMID 25781993, 2015). "Surprisingly, EPI-001 also inhibited growth of AR-negative PC-3 and DU 145 cell lines, as well as the T47D breast carcinoma cell line." (PMID 25669987, 2015). "The proliferation induced by androgens has also been demonstrated in breast cancer cell lines (MDA-MB-453) AR, ER and PgR negative when incubated with the synthetic, not metabolized androgen, Mibolerone." (PMID 26039245, 2015). "Here we provide evidences, using various preclinical models that non-aromatizable AR agonists are anti-proliferative in breast cancer cells." (PMID 25072326, 2014). "It has been suggested that the AR is a potential druggable target in TNBC and indeed, clinical studies are currently evaluating the role of androgen deprivation in the treatment of patients with breast cancer." (PMID 24779793, 2014). "We identify a novel interaction between HES6 and E2F1 and E2F1 and the AR and show enhancement of E2F1 activity that seems to result from protein complex formation rather than increased E2F1 expression as previously found in breast cancer." (PMID 24737870, 2014). "Some years ago a so-called molecular apocrine subset of breast carcinoma has been defined by gene expression analysis, and was characterized by active AR and weak or absent estrogen receptor (ER) signalling." (PMID 25070172, 2014). "Tumoral LC3A expression was highest in AR-negative breast cancer, while tumoral BNIP3 was highest in AR-positive breast cancer." (PMID 25140630, 2014). "Although previous reports have demonstrated AR expression in breast cancer, its function in breast cancer was not quantified and compared to normal breast tissue." (PMID 25072326, 2014). "While AR has been considered a potential therapeutic target in ER–/AR + breast cancers, it has not previously been suggested as a target in ER + breast cancers." (PMID 24451109, 2014). "There is a history of targeting AR for therapy in breast cancer, although the efficacy of AR targeted treatments is moderate probably due to a lack of clear understanding of the AR signaling mechanism." (PMID 24550933, 2014). "The growth of triple negative MDA-MB-231 breast cancer cells stably over-expressing AR (MDA-MB-231-AR) was inhibited by AR agonists, but not by antagonists or structurally similar non-binders." (PMID 25072326, 2014). "The effects of AR inhibition with enzalutamide were examined in vitro and in preclinical models of ER positive and negative breast cancer that express AR." (PMID 24451109, 2014). "Although there are no studies that have explored the relationship between AR and autophagy in breast cancer, there have been studies of prostate cancer tumors, which are most representative of AR-positive tumors." (PMID 25140630, 2014).
breast carcinoma (continued). "Studies presented herein systematically evaluate non-metabolizable AR agonists, SARMs, for the treatment of breast cancer." (PMID 25072326, 2014). "The significance does not hold up for DSS; however, patients with high AR:ER ratios died from their breast cancer on average 10 months earlier than patients with low ratios." (PMID 24451109, 2014). "The purpose of this study was to investigate the expression of autophagy-related proteins in relation to androgen receptor (AR) status in estrogen receptor (ER)-negative breast cancers." (PMID 25140630, 2014). "Nevertheless, whether NILCO and targets are differentially-expressed in human breast cancer tissues, in relation to ER, PR and HER2 as well as EGFR and AR statuses, is unknown." (PMID 24716804, 2014). "DLL4, Notch1, IL-1R tI and VEGF were expressed in almost all breast cancer tissues irrespective of AR status." (PMID 24716804, 2014). "By contrast, in the apocrine breast cancer subtype- an ER negative tumor- the AR acts by binding to the same transcription factors as the ER does, mainly through FOXA1, leading to a luminal gene expression phenotype." (PMID 24779793, 2014). "This is comparable with our findings in male mice where DMBA caused enlargement of mammary lymph nodes, but not the growth of mammary tumors in either wild-type or AR knockout males for up to 39?weeks." (PMID 25928046, 2014). "Although previous studies have examined the effects of androgen based on menopausal status, the relationship between the role of the AR and the age of breast cancer patients has not been reported previously." (PMID 24403250, 2013). "Molecular apocrine (MA) tumors are estrogen receptor (ER) negative breast cancers characterized by androgen receptor (AR) expression." (PMID 23663520, 2013). "AR expression in breast cancers is independent of estrogen receptor alpha (ERα) status and is frequently associated with overexpression of the ERBB2 oncogene." (PMID 23593223, 2013). "One of the more intriguing explanations for the differential effect on proliferation in ER− and ER+ tumor cell lines may involve an interaction between AR and HER2 as both receptors are coexpressed in approximately 50% of ER− breast cancers." (PMID 24324894, 2013). "In MDA-MB-453 breast cancer cells that do not express ERα, AR activates ERBB2 signaling by direct androgen-dependent induction of WNT7B and ERBB3 expression." (PMID 23593223, 2013). "Several of the genes involved are also in signalling pathways relevant to breast cancer: ERBB2, NRIP1 and BCAS3 are involved in estrogen receptor function and APPBP2 with androgen receptor; while TAOK1 and SKAP1 are involved in MAPK signalling and DEPDC6/DEPTOR regulates mTOR signalling." (PMID 23260012, 2012). "Almost all (8 of 9; 89%) KCNMA1 amplified, but only 11 of 25 (44%) non-amplified breast cancers were AR-negative." (PMID 22899999, 2012). "First a significant percentage of breast cancers (10% to 20%) are AR-positive/ERα-negative, thus providing an opportunity for hormone therapies targeting AR in this group of patients." (PMID 22321971, 2012). "By contrast, molecular apocrine tumors may benefit from dual MEK and AR inhibition as previously reported, and similar results may also apply to HER2-positive/AR-positive breast cancers." (PMID 22321971, 2012). "Although overexpression is difficult to quantify, the complete lack of AR gene amplification strongly suggests that gene amplification is not a common event in human breast cancers." (PMID 22321971, 2012). "In addition, other hormone receptors, such as androgen receptor, utilized HSP90, which provides a rationale for the use of HSP90 inhibitors and AR antagonist in the subset of AR+ breast cancers." (PMID 22510516, 2012).